TNXB (tenascin XB)
Diseases named in the same sentence as TNXB in open-access papers (continued):
Sharing a sentence is not in itself a finding about the gene and the disease.
social anxiety disorder (3 papers, 2021 to 2025). "Tenascin XB (TNXB) is also a non-HLA expressed gene, and TNXB methylation has similarly been associated with psychiatric disorders including social anxiety disorder and anorexia nervosa." (PMID 34798907, 2021).
type 1 diabetes (3 papers, 2012 to 2023). "The TNXB gene was previously shown to be moderately implicated in type I diabetes, but a further analysis of this association is warranted regarding the HLA region and non-HLA class II genes." (PMID 37189830, 2023). "After adjustment, three additional MHC genes achieved genome-wide significant evidence of rare variant association with type 1 diabetes: HLA-DMA (P = 1.1 × 10−7), SKIV2L (P = 2.6 × 10−7) and TNXB (P = 4.1 × 10−7)." (PMID 22951892, 2012).
aneurysm (2 papers, 2024 to 2025). Bulging or ballooning in an area of an artery secondary to arterial wall weakening. "Of the 170 individuals who underwent clinical genetic screening in our program following the discovery of aneurysms, 9 unrelated patients (N = 9) who were found to have genetic variants in TNXB and arterial aneurysms were included in the study cohort." (PMID 40650310, 2025). "This presentation pattern is consistent with the often-silent progression of aneurysms and underscores the need for vigilant clinical surveillance in patients with TNXB variants." (PMID 40650310, 2025). "Several mechanisms may explain how TNXB mutations contribute to aneurysm formation, including fibrillogenesis, cell signaling, and endothelial-to-mesenchymal (EndMT) transition." (PMID 40650310, 2025). "A heterozygous variant in TNXB was found in a patient with five aneurysms." (PMID 39382597, 2024). "Incorporating genetic screening for genes such as TNXB into clinical care for patients with newly diagnosed aneurysms could help clarify the prevalence and impact of these variants and identify patients at risk for future aneurysm development." (PMID 40650310, 2025).
cervical cancer (2 papers, 2022 to 2023). A primary or metastatic malignant neoplasm involving the cervix. "The down-regulation of TNXB is observed in cervical cancer and its up-regulation is known as correlated with the inhibition of EMT, migration, and invasion in this cancer." (PMID 35333898, 2022).
cholesteatoma (2 papers, 2015 to 2023). A pathologic process characterized by the proliferation of keratinizing squamous epithelium resulting in the accumulation of keratin and cells in the middle ear and/or mastoid. "Whether altered TNXB levels in our study reflect a pathologic or reactive change to cholesteatoma remains to be seen." (PMID 26608071, 2015).
depression (2 papers, 2020 to 2025). "Of the candidate genes that were associated with depression, TNXB attracted particular attention since it was the only gene that additionally showed nominal significance in both transcriptome and methylation analyses." (PMID 39897774, 2025). "The present study identified six protein-coding genes associated with depression and primarily involved in inflammation (TNXB), neuroplasticity (NCAM1 and LTBP3), immune response (BTN3A2), cell survival (DAG1) and circadian clock modification (FHIT)." (PMID 39897774, 2025). "We have identified six protein-coding genes associated with depression and primarily involved in inflammation (TNXB), neuroplasticity (NCAM1 and LTBP3), immune response (BTN3A2), cell survival (DAG1) and circadian clock modification (FHIT)." (PMID 39897774, 2025). "Eight SNPs corresponding to six protein-coding genes (TNXB, NCAM1, LTBP3, BTN3A2, DAG1, FHIT) were identified that were highly associated with depression." (PMID 39897774, 2025). "TNXB has previously been shown to be differentially methylated in depression, and also to have altered transcriptomic profile in fibroblasts of depressive patients." (PMID 39897774, 2025). "Our finding of TNXB is consistent with previous evidence to support the role of inflammation in the pathophysiology of depression." (PMID 39897774, 2025). "Our findings confirmed previous evidence for TNXB- and NCAM1 in the pathophysiology of depression and suggested four new potential candidate genes (LTBP3, BTN3A2, DAG1 and FHIT) that warrant further investigation." (PMID 39897774, 2025). "Our findings confirmed previous evidence for TNXB- and NCAM1 in the pathophysiology of depression and suggested new potential candidate genes (LTBP3, BTN3A2, DAG1 and FHIT) that warrant further investigation." (PMID 39897774, 2025).
Ehlers-Danlos syndrome type 1 (2 papers, 2024 to 2025). "Classical-like Ehlers-Danlos Syndrome type 1 is caused by the TNXB gene and affects less than one in a million people." (PMID 39480826, 2024).
Ehlers-Danlos syndrome type III (2 papers, 2014 to 2024). "One of these, TNR coding for tenascin R, is a candidate gene for PL, because mutations in one of its paralogues, TNXB, are known to cause Ehlers-Danlos syndrome type III in humans (omim:130020)." (PMID 24886090, 2014).
gastric adenocarcinoma (2 papers, 2023 to 2025). "Western blotting and immunohistochemical experiments have indicated that TNXB is overexpressed in patients with gastric adenocarcinoma with lymph node metastasis, which is linked to a lower survival rate in these patients and can serve as a prognostic marker." (PMID 40606972, 2025).
joint diseases (2 papers, 2012 to 2022). "However it is notable that CILP2, like other high-scoring plasma protein markers such as COMP, TNXB, THBS4, SPP1, COL2A1 to name a few, are associated with connective tissue development (cartilage matrix synthesis in the case of CILP2) and bone and joint disorders." (PMID 22558154, 2012).
keratoconus (2 papers, 2023 to 2026). A degenerative, structural disorder of the eye, characterized by a cone-shaped protrusion of the cornea. "The presence of a TNXB or COL5A1 mutation (related to EDS) in a keratoconus patient might prompt screening for mitral valve prolapse or vessel fragility, for instance." (PMID 41595486, 2026). "A recent study utilized whole exome sequencing (WES) to identify 34 keratoconus-related genes and noted genetic variation for several genes that are pertinent to EDS, including COL5A1, TNXB, ZNF469, and COL12A1." (PMID 37374145, 2023).
Lipedema (2 papers, 2020 to 2024). Disorder of adipose tissue characterized by symmetric and bilateral enlargement of the lower extremities due to abnormal deposition of subcutaneous fat often in obese women. "For example, there are multiple reported genes that can confer a lipedema phenotype to tissue, and two of these genes affect tissue elasticity: ELN and TNXB (tenascin-X gene)." (PMID 33786515, 2020).
lymph node metastasis (2 papers, 2023 to 2025). "Our study found for the first time that TNXB and SPON1 are highly expressed in the primary tumor tissues of GAC patients with lymph node metastasis, and that overexpression of TNXB and SPON1 is associated with poor prognosis of GAC patients." (PMID 36520032, 2023). "We discovered overexpression of TNXB and SPON1 in patients with lymph node metastasis, which correlates with poor survival of GAC patients." (PMID 36520032, 2023).
malignant mesothelioma (2 papers, 2023). A malignant neoplasm of the pleura or peritoneum, arising from mesothelial cells. "TNXB is overexpressed in malignant mesothelioma tumor tissues comparing to normal tissues, and it is also a new diagnostic marker of malignant mesothelioma." (PMID 36520032, 2023). "Furthermore, TNXB is significantly expressed in malignant mesothelioma." (PMID 37954130, 2023).
Obesity (2 papers, 2023 to 2024). Accumulation of substantial excess body fat. "Given that children’s obesity outcomes have been linked to the genes PRLHR and TNXB, these genes need further study." (PMID 37239458, 2023).
serous ovarian cancer (2 papers, 2010 to 2015). "That is, one group including: SSBP1, IFI6 DDT, IFI27, C11orf92, NFKBIA, TNXB, NEAT1 and TFG, was up-regulated in most patients with stage III serous ovarian cancer." (PMID 20969748, 2010).
vesicoureteral reflux (2 papers, 2015 to 2017). Abnormal flow of urine from the urinary bladder back into the ureters. "In addition, although a deleterious heterozygous mutation in TNXB (Thr3257Ile) has been shown to cause hereditary vesicoureteral reflux (VUR), this was not true for the SNP detected in the present study (rs6457477; Arg504His)." (PMID 29197384, 2017).
acute myocardial infarction (1 paper, 2021). Necrosis of the myocardium, as a result of interruption of the blood supply to the area. "One study of left ventricular dysfunction after acute myocardial infarction reported a panel of three genes (TNXB, TGFBR1, and LTBP4) that could potentially improve the prediction of post-myocardial infarction heart failure." (PMID 34071145, 2021).
adenoma (1 paper, 2022). A neoplasm arising from the epithelium. "In adenomas with early carcinomas, statistically significant results include TNXB with 7.7-fold downregulation (p ≤ 0.001), 4.4-fold upregulation of CDK1 (p ≤ 0.01), 14.1-fold upregulation of ANLN (p ≤ 0.001), and 26.3-fold upregulation of ECT2 (p ≤ 0.001)." (PMID 36362041, 2022). "Statistically significant results in adenomas include 12.4-fold downregulation of TNC (p ≤ 0.001), 9.4-fold downregulation of TNXB (p ≤ 0.001), and 6.0-fold upregulation of ECT2 (p ≤ 0.001)." (PMID 36362041, 2022).
adhesive capsulitis (1 paper, 2016). "In the present study, we quantified the mRNA expression of the TGFβ1, TGFβR1, LOX, PLOD1, PLOD2, COMP, FN1, TNC and TNXB genes in glenohumeral synovium/capsule samples collected from patients with adhesive capsulitis and from controls." (PMID 27438566, 2016).
anxiety disorder (1 paper, 2021). A category of psychiatric disorders which are characterized by anxious feelings or fear often accompanied by physical symptoms associated with anxiety. "The stress environmental factors like early life adversity would trigger the DNA methylation change (Provençal and Binder, 2015), and epigenome-wide association study (EWAS) have reported many genes that showed epigenetic changes in anxiety disorders, including CFAP46, SLC43A2, and TNXB." (PMID 34650599, 2021).
atherosclerosis (1 paper, 2023). A disease characterized by the build-up of fatty material and calcium deposition in the arterial wall resulting in partial or complete occlusion of the arterial lumen. "TNXB haploinsufficiency or deficiency may provide some benefit to vascular events such as stroke by attenuating aging-related atherosclerosis and enhancing the body's adaptation to atherosclerotic plaques." (PMID 36959823, 2023). "TNXB plays a role in inhibiting endothelial-to-mesenchymal transition (EndMT) and endothelial inflammation, thus ameliorating atherosclerosis by binding to TGF-beta and blocking its activity." (PMID 36959823, 2023).
benign breast diseases (1 paper, 2023). "Moreover, in this study, TNXB was detected in the serum samples of all patients diagnosed with benign breast diseases and LN-negative cancer patients, but not in LN-positive patients, indicating that loss of circulating TNXB could be used as a biomarker of LN metastasis." (PMID 38067168, 2023).
brittle cornea syndrome (1 paper, 2026). Brittle cornea syndrome is a form of Ehlers-Danlos syndrome characterized by a severe ocular manifestations due to extreme corneal thinning and fragility with rupture in the absence of significant trauma, and progression to blindness. "Notably, COL5A1 and COL12A1 mutations underlie classical EDS, TNXB mutations cause a form of EDS with tenascin-X deficiency, and ZNF469 as mentioned is linked to brittle cornea syndrome (sometimes considered an EDS-like condition)." (PMID 41595486, 2026).
celiac disease (1 paper, 2023). An autoimmune genetic disorder with an unknown pattern of inheritance that primarily affects the digestive tract. "The most notable findings were the striking associations of the TNXB gene, responsible for the glycoprotein tenascin XB, with celiac or tropical sprue, celiac disease, and, in particular, with diabetic type I neuropathy (p value < 5 × 10−8)." (PMID 37189830, 2023).
colorectal tumors (1 paper, 2025). "Barrow and colleagues (2017) discovered significant hypomethylation of four loci associated with the TNXB gene in adjacent mucosa from active smokers when compared to never smokers in colorectal tumors." (PMID 40806327, 2025).
diabetes (1 paper, 2023). "The TNXB gene was additionally linked, through PheWAS, with the use of insulin 1 year after the diagnosis of diabetes and the general use of insulin, further implicating TNXB in the pathology of diabetes and diabetic neuropathy, as previously shown." (PMID 37189830, 2023).
dissection (1 paper, 2025). The separation and isolation of tissues for surgical purposes, or for the analysis or study of their structures. "Three additional TNXB variants were identified in two individuals not included in this study cohort: c.3149-3C>T in a patient with cEDS and Q961R/V882M in a patient with a family history of multiple aortic dissections." (PMID 40650310, 2025).
esophageal squamous cell carcinoma (1 paper, 2023). Esophageal squamous cell carcinoma (ESCC) is a type of esophageal carcinoma (EC) that can affect any part of the esophagus, but is usually located in the upper or middle third. "Moreover, it has been revealed that a functional variant in the TNXB promoter is associated with risk of esophageal squamous-cell carcinoma (ESCC) in the Chinese population, leading to the expression of TNXB being downregulated in ESCC tissues." (PMID 37007968, 2023).
fibromyalgia (1 paper, 2014). A chronic disorder of unknown etiology characterized by pain, stiffness, and tenderness in the muscles of neck, shoulders, back, hips, arms, and legs. "Fibromyalgia has been genetically linked to the HLA region (6p21.3) 63, which includes several genes associated with Notch signalling (e.g. Notch4, FKBP5, TNXB, MTCH1 and TNF-a) or with stem cell maintenance and proliferation (e.g. POU5F1, Flot1, MAPK14, Rgl2 and Rab44)." (PMID 25164209, 2014).
glioma (1 paper, 2024). A benign or malignant brain and spinal cord tumor that arises from glial cells (astrocytes, oligodendrocytes, ependymal cells). "While mutations in EFEMP2, ADAM10, SERPINH1, ADAM15, GAS6 and TNXB were detected only in patients with glioma grade 3, mutations in LTBP2, DCN, CRELD1 and HAPLN3 were observed only in patients with glioma grade 4, GBM." (PMID 38272115, 2024).
Headache (1 paper, 2020). Cephalgia, or pain sensed in various parts of the head, not confined to the area of distribution of any nerve. "Another gene TNXB (tenascin XB) was also found in the present study to track with headache in breachers with high cumulative blast exposure." (PMID 33192958, 2020).
hepatocellular carcinoma (1 paper, 2022). A malignant tumor that arises from hepatocytes. "Under pathological conditions, TNXB transcript dramatically decreased in most cancers, including hepatocellular carcinoma, thus corroborating our result." (PMID 35878242, 2022).
hyperandrogenemia (1 paper, 2023). "In the course of Sanger sequencing for the CYP21A2 gene downstream of the TNXB gene, the 46 patients with hyperandrogenemia were previously identified by our group as carriers for the p.Gln319Ter pathogenic variant." (PMID 37324257, 2023).
IgA nephropathy (1 paper, 2023). "In this study, the pathological diagnosis of the proband’s sister (II-2) confirmed IgA nephropathy, and genetic testing suggested a mutation in the Col4A4 and TNXB gene." (PMID 37323683, 2023).
invasive breast carcinoma (1 paper, 2020). A carcinoma that infiltrates the breast parenchyma. "As a next step we compared the expression levels of tenascin genes (TNC, TNN, TNR, TNXB) in invasive breast cancer using GEPIA program." (PMID 32817625, 2020).
keloid (1 paper, 2024). An irregularly shaped, elevated mark on the skin caused by deposits of excessive amounts of collagen during wound healing. "Of those, six genes (i.e., OPCML, S100A7, S100 calcium binding protein A8 [S100A8], KANK4, PTPRD, tenascin XB [TNXB]) were significantly differentially expressed between keloid and immature scar samples." (PMID 38622256, 2024).
mesothelioma (1 paper, 2022). A usually malignant and aggressive neoplasm of the mesothelium which is often associated with exposure to asbestos. "The TNXB (tenascin XB) gene was first implicated in Ehlers–Danlos syndrome, but its role in several human cancers have been established, including nasopharyngeal and mesothelioma." (PMID 35054365, 2022).
myxofibrosarcoma (1 paper, 2013). A malignant fibroblastic neoplasm arising from the soft tissue. "The genes, WNT1 inducible signaling pathway protein 2 (WISP2), G protein-coupled receptor 64 (GPR64) and Tenascin XB (TNXB) were found to be upregulated in myxofibrosarcoma compared with other spindle cell and pleomorphic sarcomas." (PMID 24216705, 2013).
pancreatic cancer (1 paper, 2023). "FGF7 and TNXB (tenascin X plays a role in organizing and maintaining the structure of muscle tissues, connective tissues, etc., by producing and assembling certain types of collagen) can increase pancreatic cancer cell migration and invasion." (PMID 37070074, 2023). "These genes were overlapped with 9,170 DEGs in PAAD, which were obtained by comparing the mRNA expression profile between pancreatic cancer in TCGA and the normal pancreas in GTEx; six specific genes were found, including VWF, GNG11, FGF7, TNXB, IL3RA, and LPAR1." (PMID 37070074, 2023).
panic disorder (1 paper, 2021). An anxiety disorder characterized by multiple unexpected panic attacks with persistent concern of recurring attacks. "Several studies also suggest a genetic and epigenetic association between TNXB and psychiatric disorders such as schizophrenia or anorexia nervosa and, strikingly, hypomethylation of a CpG site in intron 6 of TNXB has already been associated with panic disorder in an EWAS12." (PMID 33542190, 2021).
polyarticular JIA (1 paper, 2022). "CRLF1, MFAP5, and TNXB are overexpressed in persistent oligoarticular JIA FLS compared to polyarticular JIA FLS." (PMID 36167601, 2022).
Pulmonary hemorrhage (1 paper, 2025). Pulmonary hemorrhage is a bleeding within the lungs. "Two novel and two pathogenic mutations in COL3A1 gene associated with vEDS, COL1A1, COL1A2, TNXB gene mutations of non-vascular types underlying EDS and COL4A2 gene associated with collagen synthesis were found in patients presenting with pulmonary hemorrhage." (PMID 40598578, 2025).
sarcoma (1 paper, 2021). A usually aggressive malignant neoplasm of the soft tissue or bone. "Differentially methylated regions and genes were detected, not been previously implicated in sarcoma progression, including at PTPRN2 and DAXX in LMS, WT1-AS and TNXB in SS, VENTX and NTRK3 in pleomorphic RMS and MEST and the C14MC / miR-379/miR-656 in MFS." (PMID 33436720, 2021).
skin cancer (1 paper, 2021). "We found that high methylation level in cg20614157 was associated with higher frailty; a previous study has found that high methylation of the CpG site is associated with low expression of TNXB in breast and skin cancer tissues (Broad Institute of MIT & Harvard, 2016)." (PMID 34431594, 2021).
synovial sarcoma (1 paper, 2025). "recently reported TNXB hypomethylation in metastatic synovial sarcoma compared to primary tumor tissue, in line with our findings." (PMID 40145859, 2025).
ventricular septal defect (1 paper, 2019). The presence of a defect (opening) in the septum that separates the two ventricles of the heart. "An interesting CNV in eight PA-VSD patients and two TOF patients at the 6p21.33 locus was observed as a recurrent rare event, and the gain CNV overlapped the TNXB gene, which was reported to be highly expressed in fetuses and pregnancies with isolated ventricular septal defects (VSD)." (PMID 30745907, 2019).